CD177 (CD177 molecule)
Diseases named in the same sentence as CD177 in open-access papers (continued):
Sharing a sentence is not in itself a finding about the gene and the disease.
polycythemia vera (10 papers, 2010 to 2025). "In recent years, studies reveal that CD177 is related to some diseases including polycythemia vera and thrombocytopenia, and CD177 has been a diagnostic marker of some diseases (such as polycythemia vera, thrombocytopenia, and idiopathic myelofibrosis)." (PMID 31093484, 2019). "CD177 has been established as a diagnostic marker for various myeloproliferative diseases including polycythemia vera, thrombocythemia, and idiopathic myelofibrosis." (PMID 25359465, 2015). "CD177 is a polymorphic gene that has been linked to several important clinical diseases including polycythemia vera, Wegner’s granulomatosis, and immune mediated neonatal neutropenia." (PMID 25359465, 2015). "Furthermore, the expression level of CD177 has been closely linked to the severity and prognosis of polycythemia rubra vera." (PMID 41142798, 2025). "In addition, CD177 has been a diagnostic marker for some diseases such as polycythemia vera, thrombocytopenia, and idiopathic myelofibrosis." (PMID 31093484, 2019). "Furthermore, elevated levels of neutrophil CD177 mRNA are associated with increased neutrophil production and quantitation of neutrophil CD177 mRNA is a diagnostic tool for polycythemia vera." (PMID 26024230, 2015). "Overexpression of CD177 has been observed in patients with polycythemia rubra vera and polycythemia." (PMID 41142798, 2025). "CD177 is over-expressed in neutrophils from patients with myeloproliferative disorders including polycythemia vera, essential thrombocythemia, idiopathic myelofibrocythemia, and hypereosinophilic syndrome." (PMID 39131159, 2024). "As an important biomarker for polycythemia vera and essential thrombocythemia, CD177 plays a pivotal role in myeloid proliferation and differentiation." (PMID 39131159, 2024). "Previous studies confirmed that CD177 is a neutrophil-specific marker involved in the pathogenesis of conditions such as systemic vasculitis, asthma, and polycythemia vera." (PMID 37048616, 2023). "In recent years, some studies have revealed that CD177 is closely related to some diseases due to inflammation dysregulation, such as polycythemia vera and thrombocytopenia." (PMID 31093484, 2019). "As an important biomarker, HNA-2 (CD177) is over-expressed in neutrophils from patients with myeloproliferative disorders including polycythemia vera, essential thromobocythemia, idiopathic myelofibrocythemia, and hypereosinophilic syndrome." (PMID 26024230, 2015). "It is known that neutrophil CD177 expression can increase significantly in certain clinical conditions, such as severe bacterial infections and polycythemia vera." (PMID 24926686, 2014). "Recent studies have demonstrated that CD177 is over-expressed in neutrophils from 95% of patients with polycythemia vera and in half of patients with essential thrombocythemia." (PMID 23899160, 2013). "CD177 is elevated in patients with polycythemia rubra vera and thalassemias." (PMID 32487996, 2020). "HNA-2 is also known as PRV-1 as CD177 mRNA is over-expressed in polycythemia rubra vera patients." (PMID 26024230, 2015). "CD177 expression is increased in individuals with severe bacterial infections and polycythaemia vera, but not rheumatoid arthritis." (PMID 20941359, 2010).
inflammatory bowel disease (9 papers, 2018 to 2025). A spectrum of small and large bowel inflammatory diseases of unknown etiology. "Recent studies have confirmed that the CD177+ neutrophil subgroup in inflammatory bowel disease can release substantial amounts of ROS and NETs, establishing a strong antibacterial barrier." (PMID 38226808, 2024). "CD177+ neutrophil play a protective role in the development of inflammatory bowel disease, indicating a role of CD177 in inflammation." (PMID 39131159, 2024). "One recent study reported that targeting CD177+ neutrophils may be beneficial for treating inflammatory bowel disease." (PMID 30943984, 2019). "Interestingly, CD177+ neutrophils are the functionally activated neutrophil population in inflammatory bowel disease and negatively regulate disease." (PMID 30356867, 2018). "Understanding the CD177-TREM-1 axis is particularly relevant in inflammatory diseases such as inflammatory bowel disease (IBD), where dysregulated immune responses are common." (PMID 41226426, 2025). "Previous study has demonstrated that CD177+ neutrophils play a protective role in the pathogenesis of inflammatory bowel diseases (IBD) through increased IL-22 production and bactericidal activity." (PMID 36729914, 2023). "Moreover, CD177 is a glycoprotein that is exclusively expressed on neutrophils, and CD177+ neutrophils release more ROS, MPO, and calprotectin, and produce more NETs than CD177–neutrophils inflammatory bowel diseases (IBD)." (PMID 39935468, 2025).
influenza (7 papers, 2018 to 2025). An acute viral infection of the respiratory tract, occurring in isolated cases, in epidemics, or in pandemics; it is caused by serologically different strains of viruses (influenzaviruses) designated A, B, and C, has a 3-day incubation period, and usually lasts for 3 to 10 days. "We noted that CD177 was the most abundant transcript in severe influenza illness compared to moderate illness and healthy control subjects (p < 0.0001)." (PMID 32066441, 2020). "Using flow cytometry analysis (Supplementary Method), we found that CD177 protein expression in blood also distinguished between moderate and severe influenza (p = 0.038)." (PMID 31366921, 2019). "We also assessed the protein expression of the CD177 gene, the most upregulated differentially expressed gene in patients with severe influenza." (PMID 31366921, 2019).
myeloproliferative disorder (6 papers, 2012 to 2025). A clonal hematopoietic stem cell disorder, characterized by proliferation in the bone marrow of one or more of the myeloid (i.e., granulocytic, erythroid, megakaryocytic, and mast cell) lineages. "HNA-2 deficiency, observed in 3-5% of the population, arises mainly from abnormal CD177 mRNA splicing or transcriptional silencing and is strongly associated with myeloproliferative disorders (MPDs)." (PMID 41451221, 2025). "It is possible that the selection pressure to limit the spread of myeloproliferative disorders during evolution may be an important factor in maintaining the CD177 nonsense polymorphism in humans." (PMID 26024230, 2015). "HNA-2 is coded by CD177 gene that associates with human myeloproliferative disorders." (PMID 26024230, 2015). "Therefore, the CD177 SNP 829A>T may be an important genetic risk factor for various myeloproliferative disorders." (PMID 26024230, 2015). "CD177, predominantly expressed in neutrophils, serves as a valuable biomarker for myeloproliferative diseases." (PMID 40041860, 2025). "Human neutrophil antigen 2 (HNA-2) is coded by CD177 gene that involves in human myeloproliferative disorders." (PMID 26024230, 2015). "Intriguingly, in our study, WF PMN showed elevated CD177 expression, an important marker of myeloproliferative diseases." (PMID 23118879, 2012). "CD177 overexpression may also have a direct role in the pathogenesis of myeloproliferative disorders as CD177 enhances cell proliferation in vitro." (PMID 39131159, 2024). "According to the clinical study, patients with Ph-negative chronic myeloproliferative disorders showed and increased expression of CD177 as a result of abnormal proliferation of CD177+ neutrophils in the circulation." (PMID 36230605, 2022).
ovarian carcinoma (6 papers, 2011 to 2025). A malignant neoplasm originating from the surface ovarian epithelium. "In order to scrutinize the initiating cell status and identity of iOVCAR-3-OSKM cells, we evaluated the expression levels of several ovarian cancer initiating cell (OCIC) markers that previously reported like CD133, CD177, CD24, CD44, ABCG2, and ALDH1 in cells." (PMID 36085021, 2022).
leukemia (5 papers, 2014 to 2025). A malignant (clonal) hematologic disorder, involving hematopoietic stem cells and characterized by the presence of primitive or atypical myeloid or lymphoid cells in the bone marrow and the blood. "CD177 positivity was confirmed by FACS in the putative LIC population (now defined as CKFG/CD177hi) in both APLs and NPM1c+ leukemias." (PMID 38280853, 2024). "Six genes were identified in baboons (WNT3, POU2AF1, CCR7, ARG2, CD177, and WLS) and validated in human leukemia patients exposed to radiotherapy." (PMID 33737626, 2021).
neutropenia (5 papers, 2010 to 2025). A decrease in the number of neutrophils found in the blood. "The NB1/CD177 glycoprotein was initially identified in several cases of neonatal neutropenia, where the maternal antibodies react specifically with neonatal neutrophil-specific epitope HNA-2a derived from NB1 glycoprotein." (PMID 25359465, 2015). "The neutrophil surface lipoprotein CD177 (fold change [FC] = 45.1), first described in neonatal neutropenia and the mast cell protein MCEMP1 (FC = 11.4), involved in mast cell maturation, were identified as the most strongly differential expressed genes in both cohorts." (PMID 40036168, 2025).
rheumatoid arthritis (5 papers, 2008 to 2025). A chronic, systemic autoimmune disorder characterized by inflammation in the synovial membranes and articular surfaces. "Similarly, elevated expression of CD177 on neutrophils in the peripheral blood of patients with rheumatoid arthritis (RA) has been observed, alongside increased production of ROS, which can be effectively inhibited by methotrexate (MTX)." (PMID 41142798, 2025).
vasculitis (5 papers, 2013 to 2019). "The proportion of neutrophils expressing CD177 in an individual typically remains stable over time but rises in pregnancy, sepsis, and pathologic conditions including polycythemia vera, vasculitis, and SLE." (PMID 30886615, 2019). "The circulating levels of CD177+ neutrophils are increased in patients with anti-neutrophil cytoplasmic antibodies (ANCA)-dependent vasculitis." (PMID 30356867, 2018). "Our discovery cohort comprised 40 patients with systemic vasculitis (cohort 1), and emerged as part of investigation of expression of vasculitis-associated autoantigens (proteinase 3 (PR3), myeloperoxidase, and the associated alloantigen CD177)." (PMID 27227454, 2016). "CD177 may be of interest in vasculitis, as it can mediate the tethering of PR3, the target of c-ANCA autoantibodies to the neutrophil surface." (PMID 30886615, 2019). "Implication of CD177+ or CD177– populations in ANCA-derived vasculitis or other inflammatory diseases remain unknown." (PMID 28560557, 2018). "Binding of ANCA to CD177 positive (and thereby PR3 positive) cells activates them, and it has been proposed that having a high proportion of CD177-positive neutrophils confers an increased risk of developing vasculitis." (PMID 23922742, 2013).
asthma (4 papers, 2013 to 2025). "Whole peripheral blood cells from non-asthmatic control subjects (n = 17) and patients with mild asthma (n = 7), moderate but persistent asthma (n = 4), or acute asthma (n = 6) were analyzed for IL-17A expression in CD177+ neutrophils." (PMID 23822853, 2013). "The CD177+IL-17+ neutrophils percentage was highest in patients diagnosed with mild asthma, as compared to that in those with moderate asthma (P = .0108) or acute asthma (P = .0001)." (PMID 23822853, 2013). "The percentage of CD177+ neutrophils in whole blood of asthmatic patients was higher than in healthy controls and highest in the moderate asthma group." (PMID 23822853, 2013). "Furthermore, the percentage of CD177+IL-17+ neutrophils was elevated in patients with mild asthma, whereas the CD4+ IL-17+ lymphocyte population was higher in asthmatic patients and highest in those with moderate but persistent asthma." (PMID 23822853, 2013).
chronic myelogenous leukemia (4 papers, 2012 to 2024). "On the other hand, the low percentage of CD177 positive neutrophil is significantly associated with myelodysplastic syndrome and chronic myelogenous leukemia." (PMID 39131159, 2024). "Low percentages of CD177+ neutrophils are significantly associated with myelodysplastic syndrome and chronic myelogenous leukemia." (PMID 39131159, 2024).
Kawasaki disease (4 papers, 2019 to 2026). A rare inflammatory disease characterized by an acute febrile, systemic, self-limiting, medium-vessel vasculitis primarily affecting children. "Five biomarkers-CD177, Matrix Metallopeptidase 9, Nuclear Factor Erythroid 2, Colony Stimulating Factor 3 Receptor, and Suppressor Of Cytokine Signaling 3-were consistently upregulated in Kawasaki disease and showed high diagnostic accuracy (area under the curve >0.94 in both datasets)." (PMID 41743406, 2026). "Studies have found that CD177+ neutrophils are mainly enriched in patients with Kawasaki disease (KD) and multisystem inflammatory syndrome in children (MIS-C), especially in the acute stage." (PMID 41142798, 2025).
myelodysplastic syndrome (4 papers, 2015 to 2025). A clonal hematopoietic disorder characterized by dysplasia and ineffective hematopoiesis in one or more of the hematopoietic cell lines. "Additionally, CD177 serves as a valuable flow cytometry (FCM) marker for myelodysplastic syndrome (MDS)." (PMID 41142798, 2025).
periodontitis (4 papers, 2021 to 2025). An acute or chronic inflammatory process that affects the tissues that surround and support the teeth. "The proportion of CD177+ neutrophils in the circulation was found to be significantly elevated in the periodontitis patient group in comparison with the HC group." (PMID 40290655, 2025). "Curiously, CD177+ cells predominate in gingival crevicular fluid (GFC) during periodontitis, while the CD177- population predominates under healthy conditions." (PMID 36292925, 2022). "A high proportion of CD177-expressing neutrophils have also been found in the gingival crevicular fluid (GCF) of periodontitis patients." (PMID 35069541, 2021).
pneumonia (4 papers, 2020 to 2025). An acute, acute and chronic, or chronic inflammation focally or diffusely affecting the lung parenchyma, caused by an infection in one or both of the lungs (by bacteria, viruses, fungi, or mycoplasma.). "The percentage of CD177+ neutrophils was increased in the peripheral circulation of patients with new coronal pneumonia, particularly in cases of severe pneumonia." (PMID 41142798, 2025). "CD177, involved in the bactericidal activity of neutrophils, was significantly elevated in all pneumonia cases but not bronchitis cases, indicating neutrophil activation, which may be beneficial to the recovery of psittacosis cases." (PMID 36119044, 2022).
systemic lupus erythematosus (4 papers, 2014 to 2025). An autoimmune multi-organ disease typically associated with vasculopathy and autoantibody production. "An imbalance in CD177+ neutrophils has been identified as a critical pathogenic mechanism in vascular inflammation, tissue necrosis, and systemic lupus erythematosus (SLE)." (PMID 41142798, 2025). "The prospect of CD177+ MFI as a diagnostic or prognostic marker for systemic lupus erythematosus." (PMID 41142798, 2025).
adenoma (3 papers, 2005 to 2025). A neoplasm arising from the epithelium. "The upregulation of MPO and CD177, markers closely associated with neutrophil activity, supports the hypothesis that innate immune responses are a driving force in the transition from adenomas to carcinoma." (PMID 40003985, 2025). "Notably, the upregulation of CD177, a marker of neutrophil activity, suggests a critical role of neutrophil-mediated responses in the transition from adenoma to carcinoma." (PMID 40003985, 2025). "We found that DEFA4 is associated with non-advanced adenoma, MPO with advanced adenoma, and CD177 with CRC, suggesting their potential as biomarkers for distinct ACS stages." (PMID 40003985, 2025).
allergic asthma (3 papers, 2013 to 2015). A asthma with a basis in a pathological type I hypersensitivity reaction. "We found that asthmatic patients that are allergic to fungi (4 out of 17) had a higher percentage of CD177+ IL-17+ neutrophils in their peripheral blood compared to patients with allergic asthma that are reactive to other allergens (P = .0001)." (PMID 23822853, 2013). "Furthermore, the percentage of CD177(+)CRTAM(+) neutrophils in peripheral blood was also elevated in patients with allergic asthma." (PMID 25221604, 2014). "IL17+CD177+ Neutrophils increase in allergic asthma patients especially when allergic to fungi." (PMID 23822853, 2013).
psoriasis (3 papers, 2011 to 2023). An autoimmune condition characterized by red, well-delineated plaques with silvery scales that are usually on the extensor surfaces and scalp. "However, the frequency of CD177+ and OLFM4+ neutrophils is not elevated in psoriasis patients compared to healthy controls, and the actual degree of heterogeneity of neutrophils in psoriasis and the underlying mechanisms remain unclear." (PMID 37736772, 2023).
Stroke (3 papers, 2014 to 2026). Sudden impairment of blood flow to a part of the brain due to occlusion or rupture of an artery to the brain. "The prevalence of CD64+ monocytes was comparable in all study groups, while that of CD177+ monocytes was higher in both stroke groups compared to controls." (PMID 24597828, 2014). "MFI of CD64 in monocytes was lower in Stroke 2 compared to Stroke 1, while that of CD177 was comparable in all study groups." (PMID 24597828, 2014). "The prevalence of CD64+ CD177+ neutrophils was lower in Stroke 2 compared to the two other study groups, and showed a tendency of elevation in Stroke 1 compared to controls." (PMID 24597828, 2014). "Building from our clinical discovery that stroke patients suffer from tPA-induced HT featured strong expression of CD177, recombinant CD177 protein (rCD177) was loaded into CP polymersomes (CP@rCD177) as nanomedicine and administrated prior to CP@tPA thrombolysis." (PMID 41881994, 2026). "The prevalence of CD177+ neutrophils was higher in both stroke groups compared to controls." (PMID 24597828, 2014). "After stroke, CBM neutrophils preferentially increased the expression levels of Cxcl2, Prok2, Ngp, Thbs1, and Cd177." (PMID 39930981, 2025).
systemic vasculitis (3 papers, 2016 to 2023). "In addition, CD177 is pertinent to systemic vasculitis, since one of the principal autoantigens, proteinase 3, is a constituent of primary granules, but is exposed on the neutrophil surface in association with CD177." (PMID 27227454, 2016). "Current studies of CD177 are mainly focused on anti-neutrophil cytoplasmic antibody (ANCA)-related systemic vasculitis." (PMID 36532018, 2022).
acute pancreatitis (2 papers, 2023 to 2024). An acute inflammatory process that leads to necrosis of the pancreatic parenchyma. "In our studies, CD177+ neutrophils are strongly associated with the severity of acute pancreatitis." (PMID 37048616, 2023). "However, the function of CD177 in regulating the generation of NETs and the development of acute pancreatitis (AP) is unclear." (PMID 37048616, 2023).
allergic reaction (2 papers, 2013 to 2017). "To address this we analyzed the percentage of CD177+ IL-17A+ neutrophils from asthmatic patients that are allergic to specific groups of allergens based on positive intradermal allergy test reactions." (PMID 23822853, 2013).
ANCA-associated vasculitis (2 papers, 2019 to 2025). "In the context of ANCA-associated vasculitis, PR3-ANCA stimulation leads to CD177-positive/mPR3-high neutrophils producing significantly greater levels of superoxide compared to their CD177-negative/mPR3-low counterparts." (PMID 41142798, 2025). "These include CD177pos neutrophils in anti-PR3 ANCA-associated vasculitis, which could be depleted or treated to interfere with the ability of CD177 to bind PR3, although non-CD177-mediated PR3 expression may limit the effectiveness of such a strategy." (PMID 30886615, 2019).